MGAT4EP (MGAT4 family member E, pseudogene)
Gene: Transcribed unitary pseudogene on chromosome 1 (202,825,186 to 202,826,320, forward strand). Ensembl gene ENSG00000184774.
Diseases named in the same sentence as MGAT4EP in open-access papers:
MGAT4EP is named in the same sentence as 5 diseases in open-access papers, as found by Europe PMC text mining. Sharing a sentence is not in itself a finding about the gene and the disease. The quoted sentences say what the papers report.
breast carcinoma (2 papers, 2021 to 2025). "These important findings reinforce the potential of MGAT4EP as a potential prognostic marker for breast cancer, assisting clinicians in identifying high-risk patients for metastasis and providing valuable insights for individualized treatment strategies." (PMID 40069131, 2025). "Using TCGA data and bioinformatics, MGAT4EP was identified as significantly overexpressed in breast cancer tissues and associated with poor prognosis." (PMID 40069131, 2025). "To further validate the function of MGAT4EP in breast cancer, we conducted RNA sequencing as well as in vitro and in vivo experiments to investigate its role in cell apoptosis, migration, and invasion, and to elucidate the specific mechanisms underlying breast cancer progression." (PMID 40069131, 2025). "To further elucidate the mechanisms by which MGAT4EP regulates the onset and progression of breast cancer, we first performed Gene Set Enrichment Analysis (GSEA) analysis on TCGA data." (PMID 40069131, 2025). "Our analysis showed that the expression of MGAT4EP was significantly higher in patients with T4 stage breast cancer compared to those with T1, T2, or T3 stages (T4 vs T1, p = .003; T4 vs T2/T3, p = .013)." (PMID 40069131, 2025). "Differential expression analysis revealed that MGAT4EP was significantly overexpressed in breast cancer tissues compared to normal tissues." (PMID 40069131, 2025). "In conclusion, this study systematically elucidates the significant potential of MGAT4EP as a prognostic marker for breast cancer and provides in-depth insight into its complex mechanisms in breast cancer biology." (PMID 40069131, 2025). "In summary, our study demonstrates that MGAT4EP plays a pivotal role in breast cancer prognosis by regulating apoptosis and significantly inhibiting tumor growth, thereby highlighting its potential as a therapeutic target." (PMID 40069131, 2025). "Further multivariate Cox regression analysis confirmed that MGAT4EP expression remained a significant factor for poor prognosis in breast cancer patients, with an HR of 2.661 (95% CI: 1.076–6.579), p = .034." (PMID 40069131, 2025). "Based on the results of previous studies, MGAT4EP has been identified as an important prognostic factor for breast cancer." (PMID 40069131, 2025). "In our previous study, we identified MGAT4EP as an important marker of poor prognosis in breast cancer patients." (PMID 40069131, 2025). "In-depth analysis revealed a strong association between MGAT4EP expression levels and clinical staging in breast cancer, particularly among patients with lymph node metastasis and distant metastasis, where MGAT4EP expression was significantly up-regulated." (PMID 40069131, 2025). "Taken together, these findings establish MGAT4EP as an attractive target for metastatic breast cancer and provide a potential a promising therapeutic target for breast cancer treatment." (PMID 40069131, 2025). "Functional studies revealed that silencing MGAT4EP via siRNA promoted apoptosis, inhibited migration and invasion in breast cancer cells." (PMID 40069131, 2025). "Through this study, we aim to elucidate the critical role of MGAT4EP in breast cancer progression, providing new insights and potential targets for both prognostic prediction and therapeutic strategies in breast cancer." (PMID 40069131, 2025). "Therefore, future research should aim to the clinical sample size and incorporate additional animal models to further validate the specific role of MGAT4EP in breast cancer and actively explore its clinical potential as a therapeutic target." (PMID 40069131, 2025). "However, whether MGAT4EP serves as an independent prognostic factor for breast cancer still requires further validation." (PMID 40069131, 2025). "MGAT4EP, a newly identified pseudogene, is localized in the cell nucleus and interacts with FOXA1, a key regulatory factor in breast cancer." (PMID 40069131, 2025).
breast carcinoma (continued). "Among the top hits, we identify a cancer-testis unitary pseudogene, MGAT4EP, that is predominantly localized in the nucleus and interacts with FOXA1, a key regulator in luminal A breast cancer." (PMID 34425866, 2021). "Consistent with the results obtained by CRISPRi method, we found that the effective siRNA-mediated depletion of MGAT4EP inhibited the growth of both MCF7 and T47D, the two independent luminal A breast cancer cell lines." (PMID 34425866, 2021). "When MGAT4EP expression was analyzed in conjunction with TNM and age, univariate Cox regression analysis revealed that MGAT4EP expression is a negative prognostic factor for breast cancer, with a Hazard Ratio (HR) of 4.513 (95% CI: 2.024–10.060), p < .001." (PMID 40069131, 2025). "To further investigate the role of MGAT4EP in breast cancer metastasis, we conducted GSEA analysis on TCGA data, which suggested that MGAT4EP may promote breast cancer metastasis by regulating cell adhesion-related pathways." (PMID 40069131, 2025).
pancreatic adenocarcinoma (1 paper, 2021). "Like MGAT4EP, MYH16 is a cancer-testis unitary pseudogene, which was upregulated in solid tumors such as pancreatic adenocarcinoma (PAAD) and showed a much higher expression in testis than other normal tissues (data not shown)." (PMID 34425866, 2021).
tumor (2 papers, 2021 to 2025). "In vivo experiments also provided important evidence of MGAT4EP’s role in tumor growth and metastasis." (PMID 40069131, 2025). "Moreover, we have also observed that the pseudogene MGAT4EP is expressed in TNBC cell lines, and its expression is significantly higher in tumor tissues compared to normal tissues." (PMID 40069131, 2025).
cancer (1 paper, 2021). A tumor composed of atypical neoplastic, often pleomorphic cells that invade other tissues. "Given that FOXM1 is an established oncogenic transcription factor which is upregulated in a variety of human cancers, we focused on characterizing the mechanism, whereby MGAT4EP/FOXA1 axis regulates its expression." (PMID 34425866, 2021). "In contrast, our study revealed a distinct evolutionary scenario, where the MGAT4EP showed a novel function in transcriptional regulation and dominant nuclear localization that was hijacked by cancer cells to increase cell fitness." (PMID 34425866, 2021). "Thus, like MGAT4EP, many other clinically relevant unitary pseudogenes may play an important role in human cancer, and further efforts are needed to characterize their functions." (PMID 34425866, 2021).
MGAT4EP also shares sentences with these, for which no sentence is quoted: lymph node metastasis (1 paper).